PHB2 (prohibitin 2)
Diseases named in the same sentence as PHB2 in open-access papers (continued):
Sharing a sentence is not in itself a finding about the gene and the disease.
Hyperglycemia (2 papers, 2022 to 2024). An increased concentration of glucose in the blood. "To probe the association between Phb2 and Pgam5-mediated mitochondrial dynamics, we transfected siRNA against Phb2 into Pgam5-silenced cardiomyocytes prior to hyperglycemia treatment." (PMID 38818468, 2024). "The study's focus on the roles of Pgam5 and Phb2 in hyperglycemia-induced myocardial dysfunction adds to the growing body of research linking mitochondrial dynamics to cardiac health under diabetic conditions." (PMID 38818468, 2024). "Initially, we observed a significant downregulation in Phb2 transcription upon hyperglycemia exposure, which was countered by Pgam5 deletion, thereby sustaining Phb2 abundance." (PMID 38818468, 2024). "The study elucidates the critical roles of Pgam5 and Phb2 in regulating mitochondrial dynamics in the setting of hyperglycemia-induced myocardial dysfunction." (PMID 38818468, 2024). "This study aimed to elucidate the protective role of Prohibitin 2 (Phb2) against mitochondrial dysfunction during hyperglycemia-induced stress in cardiomyocytes." (PMID 38818468, 2024). "The combined data suggest a protective role for both Pgam5 knockdown and Phb2 overexpression against hyperglycemia-induced cellular and mitochondrial damage." (PMID 38818468, 2024). "Overexpression of Phb2 is shown to reduce mitochondrial dysfunction and maintain cardiomyocyte viability and function during hyperglycemia stress." (PMID 38818468, 2024). "Overall, our data suggest a regulatory pathway where Pgam5 modulates mitochondrial fission and mitophagy via Phb2, offering insights into potential therapeutic targets for hyperglycemia-induced cardiomyocyte dysfunction." (PMID 38818468, 2024). "In summary, the research aligns with the broader theme of mitochondrial dysfunction in cardiac health while providing unique insights into the synergistic roles of Pgam5 and Phb2 in hyperglycemia-induced myocardial dysfunction." (PMID 38818468, 2024). "Utilizing the MTT assay, we observed that hyperglycemia significantly compromised cardiomyocyte viability, a deleterious effect that was substantially reversed upon Phb2 adenovirus transfection." (PMID 38818468, 2024). "This manuscript focuses on the role of Pgam5 and Phb2 in hyperglycemia-induced myocardial dysfunction." (PMID 38818468, 2024). "Co-immunoprecipitation (Co-IP) assay further verified that the interaction between PGAM5 and PHB2 was induced upon hyperglycemia treatment." (PMID 39285950, 2022). "Similarly, while Pgam5 deletion maintained the transcription of Parkin, Fundc1, and Bnip3, this effect was abrogated by Phb2 siRNA in hyperglycemia-treated cardiomyocytes." (PMID 38818468, 2024). "Additionally, we observed a marked increase in mitochondrial reactive oxygen species (mROS) levels upon hyperglycemia exposure, which was notably counteracted in cardiomyocytes transfected with Phb2 adenovirus." (PMID 38818468, 2024). "Furthermore, overexpression of Phb2 countered the hyperglycemia-induced mitochondrial dysfunction and normalized the levels of key mitochondrial antioxidant enzymes." (PMID 38818468, 2024). "Immunofluorescence showed that, in the presence of hyperglycemia, the interaction between PGAM5 and PHB2 was enhanced relative to the baseline." (PMID 39285950, 2022). "Herein, we found that hyperglycemia had no influence on PHB2 transcription/expression but reduced the levels of p-PHB2S91 through a mechanism dependent on the phosphatase activity of PGAM5." (PMID 39285950, 2022). "In turn, hyperglycemia-mediated PHB2 dephosphorylation at S91 was not affected by PHB2 mutants lacking the N-terminal domain (PHB2ΔN), the C-terminal domain (PHB2ΔC), or the coiled-coil domain (PHB2ΔCC) but was instead prevented by mutants lacking the PHB domain (PHB2ΔPHB)." (PMID 39285950, 2022).
melanoma (2 papers, 2014 to 2023). A malignant, usually aggressive tumor composed of atypical, neoplastic melanocytes. "In parallel, we evaluated PHB1 and PHB2 protein expressions in three groups of seven melanoma lines each representing the three major molecular subtypes (WTBRAF/WTNRAS, MUTBRAF, and MUTNRAS)." (PMID 37508519, 2023). "After optimizing the cutoff value to define low vs. high PHB groups, the Kaplan–Meier curves and Cox regression analyses demonstrated that the PHB2 mRNA expression was significantly associated with the PFS and OS in the melanoma patient cohort." (PMID 37508519, 2023).
metastatic tumor (2 papers, 2017 to 2023). "PHB2 and HSP90AB1 were overexpressed in the metastatic tumors compared with LUAD primary tumors, and high level of HSP90AB1 predicted shorter overall survival and first progression times of LUAD patients." (PMID 37742009, 2023).
Obesity (2 papers, 2020 to 2023). Accumulation of substantial excess body fat. "Prohibitins (prohibitin 1 and prohibitin 2) have been shown to play critical roles in aging, cancer, obesity, and mitophagy." (PMID 32165613, 2020).
rheumatoid arthritis (2 papers, 2024 to 2025). A chronic, systemic autoimmune disorder characterized by inflammation in the synovial membranes and articular surfaces. "Prohibitin was used as an inducer in rheumatoid arthritis and as a novel autoantigen in previous studies, suggesting that PHB1 and PHB2 might play a role as secretory proteins." (PMID 40168274, 2025).
subarachnoid hemorrhage (2 papers, 2022 to 2023). A serious neurological disorder characterized by intracranial hemorrhage into the subarachnoid space. "This indicates a possible association between Nrf2 and PHB2, which is supported by the positive correlation between Nrf2 and PHB2 expression observed in a rat subarachnoid hemorrhage model." (PMID 38077250, 2023).
adenoma (1 paper, 2023). A neoplasm arising from the epithelium. "Here in this report, we demonstrate PHB2 as a bioenergetics metabolism-related scaffolding protein, which is upregulated in precancerous adenomas and CRC and promotes cell proliferation and tumorigenesis of CRC." (PMID 36658121, 2023). "Here, we reveal that Prohibitin 2 (PHB2) expression is elevated in precancerous adenomas and CRC, which promotes cell proliferation and tumorigenesis of CRC." (PMID 36658121, 2023). "In this study, we demonstrated that PHB2, a mitochondrial inner membrane scaffolding protein, was continuously increased during the adenoma-carcinoma-metastasis sequence of CRC, which contributed to OXPHOS promotion, thereby leading to tumorigenesis and progression." (PMID 36658121, 2023). "Although our IHC results showed upregulated PHB2 in the precancerous adenoma, primary and metastatic stages of CRC, there was increased expression of PHB2 in primary CRC but not in metastatic CRC from the TCGA database analysis." (PMID 36658121, 2023).
age-related hearing loss (1 paper, 2021). "Moreover, PHB is an important paralog of PHB2, which has been described to be expressed in hair cells and spiral ganglion and might be related to mitophagy in age-related hearing loss." (PMID 34829759, 2021).
amyotrophic lateral sclerosis (1 paper, 2022). Amyotrophic lateral sclerosis (ALS) is a neurodegenerative disease characterized by progressive muscular paralysis reflecting degeneration of motor neurons in the primary motor cortex, corticospinal tracts, brainstem and spinal cord. "It is not only helpful for understanding the basic mechanism of mitophagy driven by Parkin but also identifies PHB2 as a potential player in neurodegenerative diseases that are associated with dysfunctional mitochondrial quality control, including PD and amyotrophic lateral sclerosis." (PMID 36379251, 2022).
anemia (1 paper, 2024). A reduction in the number of red blood cells, the amount of hemoglobin, and/or the volume of packed red blood cells. "Although modest compared to the effect of TFAM and PHB2 expression, the data suggest an upregulation of mitophagy in ribosome insufficiency also contributes to reduced mitochondrial biogenesis and anemia." (PMID 38992436, 2024).
Anxiety (1 paper, 2013). Intense feelings of nervousness, tension, or panic often arise in response to interpersonal stresses. "The mRNA levels of the genes coding for prohibitin 2 and SLC25A5 were also significantly increased (2.5-fold) in fish that developed anxiety and related phenotypes following chronic stress exposures." (PMID 23691016, 2013).
atherosclerosis (1 paper, 2025). A disease characterized by the build-up of fatty material and calcium deposition in the arterial wall resulting in partial or complete occlusion of the arterial lumen. "However, the expression and biological functions of PHB1/PHB2 in atherosclerosis (AS) remain unclear." (PMID 40168274, 2025).
brain injury (1 paper, 2014). Acute and chronic (see also brain INJURIES, CHRONIC) injuries to the brain, including the cerebral hemispheres, CEREBELLUM, and brain STEM. "In this study, we examined PHB2 expression and cellular localization in rats after acute traumatic brain injury (TBI)." (PMID 24566151, 2014).
chronic kidney disease (1 paper, 2025). Impairment of the renal function secondary to chronic kidney damage persisting for three or more months. "Despite being extensively assessed in chronic kidney disease models, the role of PHB2 in AKI, particularly cisplatin-induced AKI, warrants further exploration." (PMID 41438218, 2025). "Although PHB2 has been detected in many chronic kidney disease models, its role in acute models, particularly cisplatin-induced AKI, requires further exploration." (PMID 41438218, 2025).
Cognitive impairment (1 paper, 2023). Abnormal cognition is characterized by deficits in thinking, reasoning, or remembering. "In conclusion, our findings indicate that PHB2 protein levels may be altered in the postmortem prefrontal cortex of schizophrenia patients and are associated with the cognitive impairments described in the pathology." (PMID 37046989, 2023). "The PHB2 levels increased in DLPFC in cases of chronic schizophrenia and were associated with cognitive impairments." (PMID 37046989, 2023). "We aimed to investigate the possible alteration in PHB2 levels in DLPFC tissue from chronic SZ subjects and its association with cognitive deficits." (PMID 37046989, 2023). "Together, these results highlight that an increase in PHB2 protein levels could contribute to the cognitive impairments described in SZ patients and could be modulated in the early stages of the disease by the cognitive enhancer IPR19." (PMID 37046989, 2023). "Moreover, our results suggest that new cognitive therapeutic strategies could modulate PHB2 protein levels and may help to counteract cognitive impairments in SZ." (PMID 37046989, 2023). "However, altered PHB2 levels in schizophrenia linked to N-methyl-D-aspartate receptor (NMDAR) activity and cognitive deficits are still unknown." (PMID 37046989, 2023). "Indeed, our results suggest that IPR19 may restore the upregulation of PHB2 in acute NMDAR hypoactivity and in both cortical neurons and astrocytes, indicating that the modulation of PHB2 could compensate for NMDAR-dependent cognitive impairments in SZ." (PMID 37046989, 2023).
colon adenocarcinoma (1 paper, 2022). "Rabdosianone I, from the medicinal herb Isodon japonicus, binds to PHB2 and ANT2, leading to a decrease in the expression level of thymidylate synthase, resulting in growth inhibition of the human colon adenocarcinoma cell line HT-29." (PMID 35164336, 2022).
colorectal adenocarcinoma (1 paper, 2023). The most common type of colorectal carcinoma. "Next, we determined PHB2 protein levels in precancerous lesions, colorectal adenocarcinoma tissues with different stages, and adjacent normal tissues by immunohistochemistry (IHC) and western blot analysis." (PMID 36658121, 2023).
deficiencies (1 paper, 2012). "Here, we show that neuron-specific inactivation of Phb2 in the mouse forebrain causes extensive neurodegeneration associated with behavioral impairments and cognitive deficiencies." (PMID 23144624, 2012).
dementia (1 paper, 2017). Loss of intellectual abilities interfering with an individual's social and occupational functions. "We have observed a reversed Phb2 pattern between mixed dementia (Mix AD VD) respect to the protein profile observed in AD." (PMID 28831118, 2017).
dominant optic atrophy (1 paper, 2024). "Additionally, the loss of PHB2 impairs the stability of Optic Atrophy 1 (OPA1), and mutations in OPA1 have been shown to be associated with dominant optic atrophy, characterized by a gradual loss of retinal ganglion cells." (PMID 39507806, 2024).
frontotemporal lobar degeneration (1 paper, 2017). "Phb2 showed a specific up-regulation in mixed dementia, while Phb1 isoforms were down-regulated in frontotemporal lobar degeneration (FTLD)." (PMID 28831118, 2017).
gastric tumour (1 paper, 2024). "In order to evaluate the clinical relevance of PHB2 in the context of GC, we examined the expression of PHB2 using IHC in a GC TMA including 66 paired human gastric tumour (T) tissues and corresponding adjacent normal (N) gastric tissues." (PMID 38200519, 2024).
glomerular disease (1 paper, 2026). "To deepen our understanding of the relationship between mitochondrial dysfunction and glomerular disease, we used Phb2-deficient mice as a model to study mitochondrial disease." (PMID 41509918, 2026). "While our study establishes the role of OMA1 in mitigating glomerular disease in PHB2-deficiency, we did not directly assess OPA1 cleavage in podocytes." (PMID 41509918, 2026). "Further studies, including the functional perturbation of the p38 pathway, are needed to assess whether targeting the p38-mTORC1 crosstalk could alleviate glomerular disease in states of mTOR hyperactivation independent of PHB2 deficiency." (PMID 41509918, 2026). "While mutations in PHB2 have not been linked to FSGS in humans, mitochondrial dysfunction is a common feature across various forms of glomerular disease." (PMID 41509918, 2026).
hyperlipidemia (1 paper, 2025). "In the present study, an enzyme-linked immunosorbent assay was used to detect PHB1/PHB2 expression in the serum of patients with hyperlipidemia." (PMID 40168274, 2025). "Our in vivo experiments demonstrated increased serum PHB1/PHB2 levels in patients with hyperlipidemia." (PMID 40168274, 2025). "Compared with the healthy subjects, PHB1/PHB2 expression was elevated in the serum of patients with hyperlipidemia." (PMID 40168274, 2025). "In this study, we detected PHB1/PHB2 expression in the serum of patients with hyperlipidemia using ELISA." (PMID 40168274, 2025).
ischemic heart disease (1 paper, 2025). "It is well known that the reduction of cardiac fibrosis is mediated by the PHB2 protein, and cardiac fibrosis is one of the main complications of ischemic heart disease." (PMID 40005961, 2025).
kidney damage (1 paper, 2025). "For example, differential methylation of PQLC2, PTPN6/PHB2, and PRPF8 has been reported to be associated with fibrosis and inflammation leading to kidney damage." (PMID 41357321, 2025).
kidney failure (1 paper, 2015). An acute or chronic condition that is characterized by the inability of the kidneys to adequately filter the blood. "Generation of triple-knockout animals with a genetic deletion of both insulin receptor and IGF-1 receptor in addition to PHB2 (Phb2pko/Insrpko/Igf1rpko) significantly alleviated renal disease, enhanced survival (Fig4D and E), improved kidney function, and delayed the onset of kidney failure (Fig5A)." (PMID 25643582, 2015).
lymphoid tumor (1 paper, 2017). "Taken together, PHB1 and PHB2 were identified to be primarily confined to the mitochondria in lymphoid tumor cell lines, including Kit225 cells." (PMID 29029444, 2017).
lymphoma (1 paper, 2017). A malignant (clonal) proliferation of B- lymphocytes or T- lymphocytes which involves the lymph nodes, bone marrow and/or extranodal sites. "Thus, concordant with prohibitin expression observed in tumor cell lines, PHB1 and PHB2 are overexpressed in lymphoid (T- and B-cell leukemia/lymphoma) and myeloid (CML) primary patient tumor cells." (PMID 29029444, 2017).
muscular atrophy (1 paper, 2015). The loss of muscle tissue due to inactivity or disease. "Strikingly, ablation of Prohibitin-2 caused a severe motor deficit and muscular atrophy in mice at P40, due to a hypomyelinating neuropathy with a severe decrease in nerve conduction velocity." (PMID 26383514, 2015).
myeloid leukemia (1 paper, 2014). A clonal proliferation of myeloid cells and their precursors in the bone marrow, peripheral blood, and spleen. "Capsaicin, a component of hot chili peppers, binds to PHB2, and this binding induces apoptosis in human myeloid leukemia cells." (PMID 25200342, 2014).
prion disease (1 paper, 2023). A transmissible disease that is caused by a protein that is able to induce abnormal folding of normal cellular proteins, leading to characteristic spongiform brain changes, which are associated with neuronal loss without an inflammatory response. "While further research is needed to confirm and explore the full role of PHB2 in prion diseases, our studies provide hope for targeting PHB2 as a therapeutic approach for neurodegenerative diseases associated with prions." (PMID 37958902, 2023). "However, the specific impact of PHB2 on mitophagy in the context of prion diseases remains unclear." (PMID 37958902, 2023). "However, the role of PHB2 in prion diseases remains unclear." (PMID 37958902, 2023).
psychosis (1 paper, 2023). "PHB2 was also increased in animal models of psychosis by blocking NMDAR and in cells treated with an inhibitor of this type of receptor." (PMID 37046989, 2023). "To investigate whether the PHB2 protein levels could be altered in the early stages of the disease, we determined the PHB2 protein levels in a mouse model of psychosis." (PMID 37046989, 2023).
pulmonary hypertension (1 paper, 2022). Increased pressure within the pulmonary circulation due to lung or heart disorder. "The key pathogenic features of pulmonary hypertension are endothelial apoptosis and vascular inflammation, which are caused by the down-regulation of Amphiregulin, accompanied by HIF-1a and BAD-mediated up-regulation of the target genes such as RRP1B, PHB2, and NCOA6." (PMID 35732465, 2022).
renal fibrosis (1 paper, 2017). A final common manifestation of a wide variety of chronic kidney diseases characterized by glomerulosclerosis and tubulointerstitial fibrosis. "At PTPN6/PHB2 cg19942083, methylation in kidney cortex associates with lower renal PTPN6 expression, higher eGFR, and less renal fibrosis." (PMID 29097680, 2017).
retinal diseases (1 paper, 2024). "In this study, we identified the AGE–RAGE pathway, which was activated in TGF-β2-induced ARPE-19 cells, as the pathway associated with the fibrosis-related regulatory activity of PHB2, The AGE–RAGE pathway has been established to be a key regulatory pathway in retinal diseases." (PMID 39507806, 2024).
Rett syndrome (1 paper, 2025). A severe neurodevelopmental disorder affecting the central nervous system. "There is also evidence for increased PHB levels in Rett’s syndrome and involvement of PHB2 in several neuropsychiatric disorders including ASD." (PMID 40779003, 2025).
sarcopenia (1 paper, 2022). Progressive decline in muscle mass due to aging which results in decreased functional capacity of muscles. "In general, decreased levels of mitophagy markers such as PINK1, parkin BNIP3, NIX, PHB2, FUNDC1, and AMBRA1 are associated with a reduced quality of life in sarcopenia associated with aging." (PMID 36561214, 2022). "In addition, reduced levels of mitophagy markers such as PINK1, Parkin, BNIP3, NIX, PHB2, FUNDC1, and AMBRA1 negatively impact sarcopenia-related muscle weakness and the quality of life in the elderly." (PMID 36561214, 2022).